IFNG (interferon gamma)
Diseases named in the same sentence as IFNG in open-access papers (continued):
Sharing a sentence is not in itself a finding about the gene and the disease.
psoriasis (continued). "While KYNU relevance to inflammation has been demonstrated in psoriasis in which epithelial cells only expressed KYNU after stimulation with IFNγ or TNFα; and combining the cytokines significantly enhanced IDO and KYNU in various cell types as much as 100 fold." (PMID 36499104, 2022). "However, a small trial with an anti-IFNγ antibody showed only minimal efficacy in the treatment of psoriasis, in contrast to inhibition of IL-17 activity." (PMID 35087513, 2021). "In the pre-biologic era, IFNγ was tested for the treatment of psoriasis." (PMID 31973112, 2020). "Finally, the adoptive transfer of Tregs from WT mice ameliorated imiquimod-induced psoriasis skin inflammation and reduced IFNγ mRNA expression in the lesional skin, revealing the importance of Tregs in an imiquimod-induced psoriasis mouse model." (PMID 33202847, 2020). "We subsequently investigated whether neutrophils isolated from patients with active psoriasis could express/produce IL-17A, IL-17F, and/or IL-17RC mRNA, either constitutively or upon incubation for 20 h with IFNγ plus LPS, R848, or IL-17A." (PMID 29719541, 2018). "However, in a small pilot study in patients with psoriasis, treatment with a humanized anti-IFNγ antibody induced improvement of histological and some clinical parameters but only minor therapeutic effects." (PMID 29971067, 2018). "In lesional skin of psoriasis patients Th1 cells and IFNγ levels are clearly increased." (PMID 27595115, 2016). "Moreover, in a small pilot study, humanized anti-IFNγ antibody has been used in the treatment of psoriasis showing only a minor therapeutic effect." (PMID 27595115, 2016). "Several cytokine genes with overall low expression but high differential effect in psoriasis (IFNG, IL12B, IL17F, and IL22) displayed higher magnitude changes with cDNA than with cRNA hybridization, whereas the highly expressed gene IL1F9 showed a higher magnitude change with cRNA hybridization." (PMID 23308107, 2013). "Given the pro-inflammatory cutaneous cytokine milieu which is present in psoriasis, we speculated that cytokines, for example tumour necrosis factor alpha (TNFα) and interferon gamma (IFNγ), may up-regulate intracutaneous PRL production." (PMID 23626671, 2013). "Also, the IL-23 model produces the least amount of Th2 activation, which in conjunction with Th17, Th22 and IFNγ are the defining elements of inflammation in psoriasis." (PMID 24386404, 2013). "Analysis of this list of DEGs in IPA indicated that several well-known key cytokine pathways (e.g., IL-17 and IFNγ) and pathways of great importance such as Role of IL-17A in Psoriasis, Atherosclerosis Signaling, and Fatty Acid Metabolism were significantly represented in the DEGs list." (PMID 22957057, 2012). "According to the classical Th1/Th2 model by which naïve Th cells differentiate into either Th1 or Th2 cells producing the defining cytokines interferon gamma (IFNγ) and interleukin (IL)-4, respectively, psoriasis was classified as a Th1 disease with a marked type 1 cytokine profile." (PMID 20594301, 2010). "While IFNγ and the IL‐17/IL‐23 axis are well established in psoriasis, IL‐4 has been shown to downregulate IL‐1β and IL‐6 production by psoriatic cells and may aid in psoriasis resolution, as observed during treatment with vitamin D3 analogues." (PMID 40926620, 2025). "Therefore, IL-27 may activate Th1-mediated response in psoriasis, such as regulating the expression of IFNγ, and may be involved in psoriasis development." (PMID 38566992, 2024). "Increased oxidative stress and inflammatory mediators including tumor necrosis factor (TNF)-α, interferon gamma (IFN-γ), interleukin (IL)-1β, IL-6, IL-12, IL-17, IL-22 and IL-23, released by activated T-cells subsets, monocytes and dendritic cells, are involved in the pathophysiology of psoriasis." (PMID 35215285, 2022).
psoriasis (continued). "Clinical practice guidelines advise screening for latent tuberculosis using interferon gamma release assay and a plain chest radiograph in order to rule out abnormal modifications at baseline, before considering initiation of a biologic agent for the management of psoriasis." (PMID 35741329, 2022). "The intradermal administration of all groups of drugs did not cause obvious histopathological damage to the main organs, including the heart, liver, spleen, lung, and kidney in the mice, demonstrating that IFNγ-sEVs do not cause systemic adverse effects when used for psoriasis therapy." (PMID 35359454, 2022). "However, the role of Th1 cells and IFNγ in psoriasis or PsA is still unclear." (PMID 35087513, 2021). "However TNFα has been shown to inhibit the following: the secretion by plasmacytoid dendritic cells (pDC) of interferon gamma (IFNγ—an immunoregulatory cytokine that induces the release of inflammatory cytokines), the proliferation of KCs, and the maintenance of psoriasis." (PMID 34691360, 2021). "Psoriasis is marked by the Th-1 and Th-17 polarization of the adaptive immune response, later followed by the increase in expression of inflammatory mediators like interferon gamma (IFN-γ), tumor necrosis factor alpha (TNF α), interleukin-2 (IL-2), and interleukin-17 (IL-17)." (PMID 33262910, 2020). "Finally, the product of IFNγ and TNFα positively associated with early non-calcified coronary burden in patients with psoriasis (n = 224; β = 0.28, p < 0.001)." (PMID 32646751, 2020). "In addition, they can serve as non-professional antigen presenting cells through up-regulation of antigen presenting molecules–MHC-I and MHC-II in certain inflammatory conditions, e.g., in psoriasis, likely in response to IFNγ or other inflammatory cytokines such as TNFα." (PMID 27467256, 2016). "Thus, the combinedtreatment with TN F and IFNG could be a more significant contributor to theactivation of keratinocytes in both psoriasis and TMME." (PMID 24455190, 2013). "We observed reduced functionality of peripheral blood CD8 T cells from psoriasis patients compared to healthy control, with a significant decrease in CD69, Granzyme B and IFNγ expression across CD8 T cell subsets following TCR-dependent stimulation." (PMID 40391222, 2025). "HCV induces the production of inflammatory cytokines such as cathelicidin, TLR9, IFNγ, TNF-α, and IL-6, all of which are key contributors to psoriasis pathogenesis." (PMID 40724556, 2025). "In psoriasis, dendritic cells secrete interleukin-12 (IL-12) and IL-23, while Th1 cells secrete tumor necrosis factor-alpha (TNF-α) and interferon-gamma (IFN-γ), and Th17 cells secrete interleukin-17 (IL-17) and interleukin-22 (IL-22)." (PMID 40585669, 2025). "The skin cells were isolated from the mice with psoriasis induced by IMQ treatment for 6 days, stimulated ex vivo, surface stained for TCRβ or TCRγδ, fixed, stained for intracellular IL-17 A and IFNγ, and analyzed by FCM." (PMID 40481552, 2025). "Total memory, central memory, effector memory, and naïve CD8 T cell subpopulations from psoriasis patients exhibited a significantly lower percentage of CD69+, Granzyme B+, and IFNγ+ cells compared to healthy controls when stimulated with anti-CD3/CD28." (PMID 40391222, 2025). "Meanwhile, Th1 lymphocytes were commonly known by generation of interferon-gamma (IFN-γ) and tumor necrosis factor-alpha (TNF-α) which contribute to inflammatory milieu in psoriasis." (PMID 40818978, 2025). "This research evaluated IFN-γ–stimulated UC-MSCs-EVs (IFNγ-sEVs) as both immunosuppressants and natural nanocarriers for an anti–miR-210 antisense oligonucleotide (ASO-210) in psoriasis." (PMID 41226338, 2025). "Serum levels of IL-27 were elevated in patients with psoriasis compared to those in healthy controls, and serum levels of IL-27 were related to psoriasis area, severity index (PASI) score, and serum levels of IFNγ." (PMID 38566992, 2024).
psoriasis (continued). "In blood from donors with psoriasis (n = 4), JNJ-77242113 inhibited IL-23–induced IFNγ production with a median IC50 value of 9 pM (range: 0.5–35 pM), indicating an inhibitory potency similar to that observed in blood from healthy volunteers." (PMID 39080319, 2024). "The subsets of T lymphocytes intensely studied in psoriasis are CD4+ T helper 1, T helper 17, and T helper 22, which secrete TNFα/IFNγ, IL-17/Il-22, as well as IL-22, respectively." (PMID 37631384, 2023). "They found that Th1 cells secreted IFNγ and TNF-α and that Th2 cells secreted IL-4, IL-5, and IL-13, thereby defining psoriasis as a Th1 disease." (PMID 38003284, 2023). "Furthermore, we confirmed that IFNγ-sEVs reduced psoriasis symptoms including thickness, erythema, and scales of skin lesions; exhausted Th17 cells, increased Th2 cells; and reduced enrichment of inflammatory cytokines such as IL-17A, IFN-γ, IL-6, and TNF-α in both spleen and skin lesions in vivo." (PMID 35359454, 2022). "IFNG transcripts were mostly expressed in lesional LP (median/section:4), IL13 (median/section:1.5) and IL17A (median/section:9) in AD and psoriasis, respectively, with an emphasized expression in upper skin layers." (PMID 36513651, 2022). "Psoriasis and CAD are however known to share certain cytokines, including IFNγ, TNF, IL-6, and IL-1793,94." (PMID 36323703, 2022). "Compared with ASO-210 just mixed with IFNγ-sEVs in the buffer (ASO-210&IFNγ-sEVs), ASO-210 loaded into EVs (ASO-210@IFNγ-sEVs) presents better symptom alleviation of psoriasis." (PMID 35359454, 2022). "Together, these results indicated that IFNγ-sEVs exhibited a synergistic immunosuppressive function with ASO-210 in IMQ-induced psoriasis-like mice, while ASO-210@IFNγ-sEVs presented stronger inhibition." (PMID 35359454, 2022). "The median number of transcript-positive cells per section for IFNG, IL13, and IL17A mRNA were 83, 4 and 11 for LP, AD, and psoriasis, respectively, thus confirming our observations from the ST analysis." (PMID 36513651, 2022). "In line, single-cell RNASeq analysis of psoriasis also indicated few transcripts per IFNG or IL17A transcript-positive cells, with a median UMI count for IFNG or IL17A of 1 per CD4+ cell and 4 per CD8+ cell." (PMID 36513651, 2022). "We next sought to investigate the therapeutic effect of IFNγ-sEVs and ASO-210@IFNγ-sEVs in treating psoriasis in a well-established IMQ-induced model, which closely resembles the human disease phenotype according to previously published studies." (PMID 35359454, 2022). "Then splenic CD4+ T cells were obtained to assess the in vivo effect of IFNγ-sEVs and ASO-210 on the immune imbalance of Th cell subsets in a psoriasis-like IMQ mouse model." (PMID 35359454, 2022). "First, we examined the cellular uptake of IFNγ-sEVs and ASO210@IFNγ-sEVs in HaCaT keratinocytes and Jurkat T cells, two key target cell types of ASO-210 in psoriasis." (PMID 35359454, 2022). "While vitiligo disease is driven by CD49a+ TRM cells producing IFNγ, CD49a- TRM cells in psoriasis mediate disease through the production of interleukin-17 (IL-17)." (PMID 34012438, 2021). "Studies from Dr. Wang’s group has established an essential role of T cell-derived cytokines, including IFNγ, IL17A and IL22, in maintaining KRT6/16 and KRT17 expression in the chronic lesion of psoriasis." (PMID 31374826, 2019). "In a recent publication, a subset of myeloid cells expressing CD5 promoting induction of IL-22, IFNγ, TNF, and granzyme B in mixed lymphocyte reaction assays was enriched in psoriasis epidermis." (PMID 29520279, 2018). "This was also the case for IFNγ-pretreated KCs, suggesting that KCs with elevated ACKR2 levels such as those found in psoriasis patients display tensile stress–induced down-regulation of expression." (PMID 29279330, 2018). "Our data suggest that STAT2 plays a role in the psoriasis pathogenesis by regulating the expression of CXCL11 and CCL5, and thereby attracting IFNγ-producing immune cells to the skin." (PMID 28472186, 2017).
psoriasis (continued). "Our study revealed increased transcripts levels of IL17A, IFNG, and FOXP3 in moderate-severe psoriasis patients." (PMID 28042206, 2016). "In our models we observed infiltration of neutrophils and IFNγ-producing CD4+ T cells to the skin, which is similar to human psoriasis." (PMID 26701909, 2015). "Apremilast is a PDE4 inhibitor that increases levels of cyclic adenosine monophosphate (cAMP), which activates the protein kinase A and modulates the cytokines involved in the immune response of psoriasis (decreases TNFα, IL23, and IFNγ and increases IL10)." (PMID 24069534, 2013). "Since pituitary PRL secretion may be regulated by IFNγ and TNFα, albeit in rodent studies, and since these cytokines and PRL have been implicated in the pathogenesis of psoriasis, we also examined whether these prototypic pro-inflammatory cytokines influence PRL and PRLR expression in the HF." (PMID 23626671, 2013). "The performance of the interferon gamma release assays (IGRAs) and tuberculin skin test (TST) was reviewed retrospectively in patients with psoriasis, inflammatory musculoskeletal diseases, or miscellaneous inflammatory conditions." (PMID 22666260, 2012). "Gene interaction analyses highlighted IFNG, IL4, IL10, MMP9 and TIMP1 in IBD; IL10, IL13 and PTGS2 in psoriasis; IL8, IL10 and PTGS2 in RA." (PMID 20444268, 2010). "Of interest, in the context of psoriasis, a Th1 disease, is the demonstration of a down regulation of the expression of ADAM33 by IFNG (Interferon-gamma), the prototypical Th1 cytokine, in airway smooth muscle cells." (PMID 18560587, 2008). "Cytokines such as interferon-gamma (IFN-γ), granulocyte-macrophage colony-stimulating factor (GM-CSF), and phosphodiesterase-4 (PDE-4) play significant roles in the pathogenesis of psoriasis, contributing to the complex inflammatory network that sustains the disease." (PMID 40948748, 2025). "Notably, HIF1A, IL-6, TNF, and IFNG were co-modulated by more than four BPs, indicating their central role in the mechanism of action of SHTLS in psoriasis treatment." (PMID 40507893, 2025). "Moreover, QL-1200186 significantly inhibited IL-12/IL-18-induced IFNγ production in vivo and alleviated IMQ-induced psoriasis-like skin inflammation in mice, which confirms the importance of these pathways in psoriasis." (PMID 37845748, 2023). "The immune dysregulation in psoriasis involves overactive T helper type 1 (Th1) and Th17 responses, leading to the production of pro-inflammatory cytokines such as tumor necrosis factor-alpha (TNF-α), interferon-gamma (IFN-γ), and interleukin-17 (IL-17)." (PMID 37700026, 2023). "IMQ-induced psoriasis-like mice were injected with phosphate-buffered saline (PBS), IFNγ-sEVs (25 mg/kg), ASO-210 (8 nmol), ASO-210&IFNγ-sEVs (8 nmol +25 mg/kg), or ASO-210@IFNγ-sEVs (8 nmol +25 mg/kg), intradermally 4 times from day 2 to day 5 to test the therapeutic effect." (PMID 35359454, 2022). "We observe that single transcripts of disease-promoting cytokines, namely IFNG for LP, IL13 for AD, and, IL17A for psoriasis initiate localized amplification cascades of specific inflammatory responder genes that collectively represent hallmarks of the respective disease pathogenesis." (PMID 36513651, 2022). "In particular, psoriasis patients exhibit DNA hypomethylation of the IFNG gene in effector “double negative” T cells that infiltrate the epidermis and contribute to inflammation." (PMID 33869291, 2021). "The JAK/STAT signaling and spleen tyrosine kinase (SYK) pathways are implicated in numerous autoimmune and inflammatory diseases (e.g. AD, psoriasis, alopecia areata), modulating a range of immune responses, including the Th2 (IL-4, IL-13, CCL18), Th1 (IFNγ), and Th17/Th22 (CCL20, S100As) pathways." (PMID 33329590, 2020). "Since both IFNγ+ and degranulating skin trNK cells produce TNFα, it is possible that skin NK cells participate in the progression of psoriasis by the production of TNFα rather than IFNγ." (PMID 32153574, 2020).
psoriasis (continued). "In active psoriasis, some CD49− TRMs as well as some CD49+ TRMs expressed both IL-17 and IFNγ." (PMID 31673756, 2019). "In psoriasis, the absence of Th2-defining cytokines [interleukin (IL)-4, IL-5, and IL-10] and the increased presence of Th1 cytokines (interferon gamma (IFN-γ), tumor necrosis factor (TNF) and IL-12) prompted researchers to classify psoriasis as a Th1-mediated disease." (PMID 31019502, 2019). "In addition to this axis representing the core of psoriasis pathogenesis, upstream cytokines (IFN-α, IFNγ, and TNFα), synergizing cytokines (IL-22 and TNFα), and downstream mediators (IL-8, IL1F9, and CCL20) complete the pathogenic puzzle." (PMID 29316717, 2018). "Other psoriasis relevant mediators such as IL-17, TNFα, and IL-1 did not induce a significant increase in IL-23 secretion, regardless of IFNγ priming." (PMID 29535706, 2018). "Interestingly, adaptive T-cell-derived cytokines IL17A, IL17F, IL17C, IL26, IFNG, IL4, and IL10 show comparable levels in skin biopsies from paradoxical and classical psoriasis." (PMID 29295985, 2018). "In the context of psoriasis CAP has been shown to induce downregulation of IL-12 and upregulation of IL-1β, IL-6, IL-8, IL-10, tumor necrosis factor α (TNF-α), interferon gamma (IFN-γ), and vascular endothelial growth factor (VEGF) mRNAs in human keratinocytes." (PMID 28925941, 2017). "One can observe that the top psoriasis genes, including IFNg genes OASL, MX1; IL17-regulated CCL20 and IL19 are not different in the PPPP/PPP as compared with normal acral skin." (PMID 27152848, 2016). "In psoriasis patients, we expected to see primarily IFNγ signatures rather than IL‐4 + IL‐13." (PMID 40926620, 2025). "However, further research is necessary to elucidate whether IFNγ-producing CD8 T memory cells in lesional skin result from the migration of circulating memory pools and activation in situ in patients with psoriasis." (PMID 40391222, 2025). "These Th cells, in turn, produce a cascade of cytokines, including IL-17, interferon-gamma (IFN-γ), tumor necrosis factor-alpha (TNF-α), and IL-22, which directly stimulate keratinocyte hyper proliferation and contribute to the inflammatory state characteristic of psoriasis." (PMID 40072672, 2025). "Notably, our analysis revealed that in contrast to psoriasis, IFNG expression showed little to no variation between healthy skin and AD, whereas increased levels of IFNG have been observed in psoriasis, particularly in lesional skin within the T-cell cluster." (PMID 40746860, 2025). "DiD-labeled native sEVs and IFNγ-sEVs were intradermally injected into the mice, and bioluminescent images of IFN-γ stimulated MSC-sEVs taken in vivo confirmed a marked accumulation of IFNγ-sEVs on the injured skin of IMQ-induced psoriasis-like mice, as compared to unstimulated native sEVs." (PMID 35359454, 2022). "Although specific anti-inflammatory signaling pathways of noscapine in psoriasis induction are undefined, based on the current study results, we proposed that noscapine's antiproliferative and anti-inflammatory effect operates through the suppression of TNF-α/IFNγ/IL-23." (PMID 35497929, 2022). "Importantly, IFNγ-sEVs significantly improved the delivery efficiency and stability of ASO-210, the antisense oligonucleotides of miR-210 block the immune imbalance and subsequent psoriasis development." (PMID 35359454, 2022). "In addition, IFNγ-sEVs reduced the PASI score, back skin thickness, inflammatory cytokine expression, and exhausted inflammatory cells such as Th17 cells in IMQ-induced psoriasis-like mice." (PMID 35359454, 2022). "Moreover, peripheral lymphocytes of the majority of psoriasis patients but not individuals without psoriasis responded to ADAMTSL5 with production of IL-17 or IFNγ." (PMID 31402919, 2019). "Similarly, in a small study, therapeutic targeting of IFNγ with a humanized anti-IFNγ (HuZAF) showed no significant efficacy in psoriasis patients." (PMID 30915067, 2019).